SATB2 (SATB homeobox 2)
Diseases named in the same sentence as SATB2 in open-access papers (continued):
Sharing a sentence is not in itself a finding about the gene and the disease.
pancreatic cancer (6 papers, 2012 to 2022). "Since SATB2 is expressed in pancreatic cancer cell lines and Pan CSCs, it could be used as a diagnostic or predictive biomarker of pancreatic cancer." (PMID 27472393, 2016). "Inhibition of SATB2 in pancreatic cancer cells suppresses cell proliferation, colony formation, cell motility, migration and invasion." (PMID 27472393, 2016). "Taken together, these data suggest that inhibition of SATB2 expression in pancreatic cancer cells and CSCs can retard cell proliferation and colony formation." (PMID 27472393, 2016). "In conclusion, our data demonstrate that chronic ethanol exposure of HPNE cells induces EMT in vitro, and oral ethanol feeding of KC mice promoted pancreatic cancer growth and development by regulating SATB2, inflammatory cytokines, PTGS‐2, stem cell markers, and pluripotency‐maintaining factors." (PMID 34859959, 2022). "Our data demonstrate that chronic ethanol exposure can induce EMT and oral ethanol feeding of KC mice promotes pancreatic cancer growth and development by regulating SATB2, inflammatory cytokines, PTGS‐2, stem cell markers, and pluripotency‐maintaining factors." (PMID 34859959, 2022). "We have described the oncogenic role of SATB2 in various cancers, including pancreatic cancer." (PMID 34859959, 2022). "In contrast, human pancreatic cancer tissues expressed high levels of SATB2 protein." (PMID 27472393, 2016). "We therefore examined whether inhibition of SATB2 attenuates EMT characteristics in pancreatic cancer cells and CSCs." (PMID 27472393, 2016). "We next examined whether inhibition of SATB2 attenuates the growth of pancreatic cancer PANC-1 and AsPC-1 cells and Pan CSCs." (PMID 27472393, 2016). "In order to understand the biological function of SATB2, we first compared its expression in HPNE cells, pancreatic cancer cell lines (AsPC-1, BxPC-3, Mia-PaCa-2, and PANC-1) and Pan CSCs by Western blot analysis and qRT-PCR." (PMID 27472393, 2016). "The biological functions of SATB2 in pancreatic cancer initiation, progression and metastasis have never been examined." (PMID 27472393, 2016). "Since SATB2 is highly expressed in human pancreatic cancer tissues and cell lines, but not in HPNE cells and normal pancreatic tissue, it can drive pancreatic cancer growth and metastasis." (PMID 27472393, 2016). "We also demonstrate that SATB2 is not expressed in normal HPNE cells, but it is highly expressed in human pancreatic cancer cell lines, CSCs and primary tissues." (PMID 27472393, 2016).
rectal cancer (6 papers, 2012 to 2025). A primary or metastatic malignant neoplasm that affects the rectum. "The differential prognostic impact of SATB2 expression in colon and rectal cancer is noteworthy and further underlines the importance of preserving a distinction between the two disease entities, which should also be considered in future validatory studies." (PMID 22333599, 2012). "Next, we examined the relationship between SATB2 expression and established clinicopathological and investigative parameters in the full cohort, colon and rectal cancer, respectively." (PMID 22333599, 2012). "Given the lack of prognostic significance of SATB2 expression in rectal cancer, we also examined whether SATB2 expression might affect response to neoadjuvant RT and/or chemotherapy in patients with rectal cancer." (PMID 22333599, 2012). "We found that high expression of SATB2 was an independent factor of good prognosis in colon but not rectal cancer." (PMID 22333599, 2012). "As data on disease recurrence was not available for this study, the impact of SATB2 on recurrence-free survival, not least local recurrence in rectal cancer, should be assessed in future studies, preferably in cohorts where this information has been recorded prospectively." (PMID 22333599, 2012). "Also, CDX2 was not evaluable in one other metastasis of rectal cancer that was negative for SATB2." (PMID 37349623, 2024).
Anxiety (5 papers, 2009 to 2021). Intense feelings of nervousness, tension, or panic often arise in response to interpersonal stresses. "Although there are no standard behavioral paradigms to analyze this in mouse models of SAS, anxiety-like behaviors can, to some extent, reflect emotional states; we found reduced anxiety-like behaviors in Satb2 CKO mice compared to control mice." (PMID 30809123, 2019). "Given the crucial role of VMN glutamatergic signaling in metabolism and anxiety, a greater number of SATB2-expressing cells in the female mHFD offspring VMN may impact these processes." (PMID 32344561, 2020). "We found that the Satb2 CKO mice exhibited hyperactivity, increased impulsivity, reduced anxiety-like behaviors, defective sensorimotor gating, and abnormal social interaction behaviors, which reflect most of the behavioral abnormalities observed in individuals with SAS." (PMID 30809123, 2019). "Haploinsufficiency for other genes in the region may also have an impact on behavior, because the individual with a 2q31.2q32.3 deletion that did not include SATB2 also had hyperactivity, anxiety, aggressiveness, and self mutilation." (PMID 19668335, 2009).
colitis (5 papers, 2020 to 2025). Inflammation of the colon. "A recent study found that intestinal epithelial cell-specific SATB2 deficiency worsened colitis and CAC in mice by altering the diversity and composition of the gut microbiota and decreasing the expression of the Cl-/HCO3-transport protein SLC26A3." (PMID 36590401, 2022). "Also, the expression of CDX2 and SATB2 has been shown to be decreased in the epithelium of patients with inflammatory bowel disease, and Satb2-deficient mice are more prone to the development of colitis and colitis-associated cancer compared with control mice." (PMID 39998677, 2025). "Special AT-rich sequence-binding protein 2 (SATB2) is a potential diagnostic and prognostic marker for CRC, but its role in colitis and CAC is unclear." (PMID 36590401, 2022). "Lack of SATB2 expression has been reported as an adverse prognostic factor in sporadic CRCs, even in those harboring MMR-d, while it was associated with lymph node metastases in colitis-associated CRC." (PMID 33228145, 2020).
Ewing sarcoma (5 papers, 2016 to 2025). A small round cell tumor that lacks morphologic, immunohistochemical, and electron microscopic evidence of neuroectodermal differentiation. "Twelve benign fibro-osseous lesions (seven ossifying fibromas and five fibrous dysplasias) of the jaw and a primary Ewing sarcoma of the jaw were also retrieved and evaluated for SATB2 and MDM2 immunohistochemistry (IHC)." (PMID 35049602, 2021). "SATB2 was positive in all 11 OSJs, including the small-cell variant, and all 12 BFOLs of the jaw evaluated, but in the case of Ewing sarcoma of the jaw, it was negative in neoplastic cells." (PMID 35049602, 2021). "This is the first study evaluating both SATB2 and MDM2 expression in OS, BFOLs, and Ewing sarcoma of the jaw." (PMID 35049602, 2021). "This study aims to determine the value of SATB2 and MDM2 immunohistochemistry (IHC) in differentiating OSJ from other jawbone mimickers, such as benign fibro-osseous lesions (BFOLs) of the jaw or Ewing sarcoma of the jaw." (PMID 35049602, 2021). "We have observed in OSA3 line not only a strong expression of the marker gene for the osteoblast differentiation, SATB2, but also a minimal expression of the EWSR1 gene, which is the principle marker gene for the Ewing Sarcoma." (PMID 27651797, 2016). "In this study, we evaluated the value of SATB2 and MDM2 IHC in differentiating OSJ from other common jawbone mimickers, such as benign fibro-osseous lesions (fibrous dysplasia and ossifying fibroma) of the jaw and primary Ewing sarcoma of the jaw." (PMID 35049602, 2021). "SATB2 was expressed in a strong intensity and diffuse staining pattern in all cases (11 OSJ, including a small-cell variant, 7 ossifying fibromas, and 5 fibrous dysplasias) except in Ewing sarcoma, where it was negative in neoplastic cells." (PMID 35049602, 2021).
ovarian mucinous tumors (5 papers, 2019 to 2025). "When used together, CK7 and SATB2 achieve an overall diagnostic accuracy of 95.3% in distinguishing primary ovarian mucinous tumors from colorectal and appendiceal metastases, outperforming traditional panels such as CK7/CK20/CDX2." (PMID 41373846, 2025). "Special AT‐rich sequence‐binding protein 2 (SATB2) can distinguish primary ovarian mucinous tumors from ovarian metastases of colorectal or appendiceal tumors." (PMID 41321186, 2025). "Special AT‐rich sequence‐binding protein 2 (SATB2) has garnered interest in gynecological pathology because of its utility in distinguishing primary ovarian mucinous tumors from ovarian metastases of colorectal or appendiceal tumors." (PMID 41321186, 2025). "The CK7+/SATB2− profile demonstrates a sensitivity of 78% and specificity of up to 99% for identifying primary ovarian mucinous neoplasms." (PMID 41373846, 2025). "SATB2 showed broad positive expression in teratoma-associated ovarian mucinous tumors and was negative in original ovarian mucinous tumors." (PMID 38672528, 2024). "Although 30% of mucinous ovarian tumors (n = 104) had IHC performed for CK7, CK20, CDX2, SATB2, and PAX8 in a prior study, we were unable to perform this diagnostic panel on all cases and could not confirm whether they were done as part of routine pathologic assessment." (PMID 36222710, 2022).
teratoma (5 papers, 2020 to 2024). A non-seminomatous germ cell tumor characterized by the presence of various tissues which correspond to the different germinal layers (endoderm, mesoderm, and ectoderm). "Brenner tumour‐associated mucinous tumours demonstrated rare SATB2 expression and more frequently calcifications and Walthard cell nests, whereas teratoma‐associated mucinous tumours showed high SATB2 expression and RNF43 mutations and were closely resembled true gastrointestinal tumours." (PMID 32885593, 2020). "Scalloped glands, subepithelial clefts, cellular stroma, and histiocyte aggregates, along with immunohistochemical markers such as CK7, CK20, CDX2, and SATB2, can aid in determining the source of PMP and assessing its biological behavior from various origins (excluding teratoma-associated tumors)." (PMID 38672528, 2024). "SATB2, another marker with high specificity for colorectal and appendiceal malignancies, is typically absent in primary MOC but diffusely expressed in teratoma-associated MOC." (PMID 39040449, 2024). "Additionally, two cases of immature teratoma and one case of AGCT were positive for SATB2." (PMID 32677969, 2020).
autism spectrum disorder (4 papers, 2009 to 2025). A spectrum of developmental disorders that includes autism, and Asperger syndrome. "The down regulation of SatB2 and Cux1 are particularly interesting as abnormal expression of both are associated with altered behavior in mice and are suspected to be a contributor to autism spectrum disorder-like symptoms in humans." (PMID 40067832, 2025). "A fourth case of a balanced translocation predicted to disrupt the SATB2 gene has been reported in an individual with autism spectrum disorder and developmental dyspraxia." (PMID 19668335, 2009). "Additionally, one individual with a balanced translocation disrupting SATB2 had autism spectrum disorder." (PMID 19668335, 2009).
inflammatory bowel disease (4 papers, 2020 to 2025). A spectrum of small and large bowel inflammatory diseases of unknown etiology. "In a recent study investigating CRCs associated with inflammatory bowel diseases (either Crohn’s disease or ulcerative colitis), the authors found that only 43% of colitis-associated carcinomas expressed SATB2, compared to 91% sporadic CRCs." (PMID 33228145, 2020). "Taken together, these findings suggest that absence of SATB2 immunoreactivity cannot reliably exclude a colorectal or small bowel origin of a carcinoma of unknown primary in the patients affected by inflammatory bowel diseases." (PMID 33228145, 2020).
non-small cell lung carcinoma (4 papers, 2012 to 2025). A group of at least three distinct histological types of lung cancer, including non-small cell squamous cell carcinoma, adenocarcinoma, and large cell carcinoma. "However, downregulated expression of SATB2 was revealed to induce EMT in non-small-cell lung carcinoma, and to promote cell proliferation and tumor progression ability in laryngeal carcinoma." (PMID 40076993, 2025).
osteonecrosis (4 papers, 2019 to 2022). A none disease characterized by death of bone tissue due to a lack of blood supply. "Enhanced SATB2 has been demonstrated to promote osteogenic differentiation of bone marrow-derived mesenchymal stem cells (hBMSCs) in patients with osteonecrosis." (PMID 31659145, 2019). "Enhanced SATB2 has been reported to promote osteogenic differentiation of BMSCs from patients with osteonecrosis induced by ethanol." (PMID 31659145, 2019). "More recently, TNF-α was revealed to induce the inhibition of SATB2 and RUNX2 expression through microRNA-31 whereby inhibiting the osteogenic differentiation of BMSCs in ethanol-induced osteonecrosis." (PMID 35505281, 2022). "In addition, TNF-α can reduce the expression of SATB2 and RUNX2 and promote osteogenic differentiation of BMSCs by decreasing microRNA-31 expression in ethanol-induced osteonecrosis." (PMID 35505281, 2022).
sarcoma (4 papers, 2020 to 2025). A usually aggressive malignant neoplasm of the soft tissue or bone. "Changes in RUNX2 and SATB2 expression were higher in one sarcoma, while in the other RUNX2 was decreased and SATB2-positive cells were completely lost." (PMID 37686526, 2023). "The other component consisted of a high-grade pleomorphic sarcoma with osteoid and chondroid matrix production, which positive for SATB2." (PMID 32280451, 2020). "The other patient presented sarcoma with BCOR-ITD of the undescribed length of duplication, with typical BCOR and SATB2 expression." (PMID 39930783, 2025). "Cyclin D1, SATB2, TLE1, and CD10 are other immunostains that are not specific but helpful in considering a BCOR rearranged sarcoma, as noted in Cases 1 and 3 in this series." (PMID 40705064, 2025). "We detected that profound changes in morphology and the immunohistochemical profile after denosumab therapy are not compatible with changes detected in the sarcomas including expression of RUNX2, SATB2, and KI-67." (PMID 37686526, 2023).
soft tissue tumors (4 papers, 2016 to 2025). "Previous studies have found that Satb2 was a particular immunohistochemical biomarker of osteoblastic differentiation and has been helpful regarding bone and soft tissue tumors." (PMID 36517907, 2022). "SATB2 is a specific immunohistochemical biomarker of osteoblastic differentiation and has been shown to be useful for both bone and soft tissue tumors." (PMID 31659145, 2019). "SATB2, a marker highly sensitive to osteoblastic differentiation, is primarily observed in both benign and malignant bone tumors with osteoblastic features, as well as in soft tissue tumors exhibiting heterogeneous bone differentiation." (PMID 40636370, 2025). "Importantly, soft tissue tumors, such as sclerosing rhabdomyosarcoma, with abundant hyalinized collagen are categorically negative for SATB2." (PMID 28058126, 2016).
Cognitive impairment (3 papers, 2015 to 2026). Abnormal cognition is characterized by deficits in thinking, reasoning, or remembering. "In this study, we deleted Satb2 in the CA1 region of the adult mouse hippocampus and observed cognitive impairments along with significant changes in soma and dendrite morphology." (PMID 42091597, 2026). "Although we cannot exclude that the decrease in local connectivity may also contribute to the cognitive impairments of CDKL5 KO mice, the behavioral deficits were largely recapitulated in Satb2+ conditional KOs and rescued in mice with Satb2-specific CDKL5 expression." (PMID 36737483, 2024).
glioblastoma (3 papers, 2017 to 2025). The most malignant astrocytic tumor (WHO grade IV). "The analyses revealed that SATB2, EZH2, SUZ12, and PCL3 are enriched in older patients with glioblastoma (GBM) with worse performance status." (PMID 33124191, 2020). "This study shows that SATB2, a key NMP, and its coactivator CBP critically contribute to glioblastoma (GBM) growth, suggesting SATB2/CBP is a therapeutic target." (PMID 33124191, 2020).
glioma (3 papers, 2020 to 2023). A benign or malignant brain and spinal cord tumor that arises from glial cells (astrocytes, oligodendrocytes, ependymal cells). "Several studies have found that FOXM1 level is upregulated in GSCs by ALKBH5, SATB2 and other molecular to keep glioma stemness." (PMID 37620304, 2023). "Further experiments demonstrated that SATB2 is rarely expressed in glioma cells expressing the differentiation markers (GFAP, TUBB3, and GALC) in human GBMs." (PMID 33124191, 2020). "SATB2 is preferentially expressed by glioma stem cells (GSCs) in GBM." (PMID 33124191, 2020). "To interrogate the functional significance of SATB2 expression in GBM malignant growth, we initially examined SATB2 expression pattern in several human GBM specimens and found that SATB2 is preferentially expressed in nuclei of glioma cells expressing the GSC markers SOX2 and OLIG2." (PMID 33124191, 2020). "As one of key nuclear matrix‐associated proteins (NMPs), SATB2 has been reported to regulate expression of certain genes during development and cancer progression, but the role of SATB2 in glioma stem cells and GBM malignant growth has not been defined." (PMID 33124191, 2020).
head and neck squamous cell carcinoma (3 papers, 2012 to 2025). A squamous cell carcinoma that arises from any of the following anatomic sites: lip and oral cavity, nasal cavity, paranasal sinuses, pharynx, larynx, and salivary glands. "To date, the role of SATB2 in chemotherapy response has only been investigated in one study on head and neck squamous cell carcinoma (HNSCC) cells, where SATB2 was demonstrated to promote chemo- and radiation resistance by modulation of ΔNp63." (PMID 22333599, 2012).
lymph node metastasis (3 papers, 2012 to 2025). "Contrary to our findings, some researchers have shown an association of SATB2 expression with depth of invasion, lymph node metastasis, distant metastases, and TNM stage." (PMID 40076993, 2025). "These factors include SATB2 expression, tumor size, lymph node metastasis, T classification, pathological stage, histological grade, surgical margin, radiotherapy and tumor recurrence." (PMID 22815795, 2012).
mucinous adenocarcinoma (3 papers, 2022 to 2025). An invasive adenocarcinoma composed of malignant glandular cells which contain intracytoplasmic mucin. "In the setting of mucinous carcinoma, SATB2 is a good diagnostic marker since secondary EMPD arising in association with mucinous carcinoma is typically of colorectal origin, and not from non-colorectal sites." (PMID 41463263, 2025).
mucinous neoplasm (3 papers, 2019 to 2022). "SATB2 is a protein with restricted expression to glandular cells of the lower gastrointestinal tract and frequent association with appendiceal mucinous neoplasms." (PMID 35272690, 2022). "Interestingly, the combined expression of CK7 and SATB2 was able to distinguish lower gastrointestinal tumours from ovarian primary mucinous tumours." (PMID 32885593, 2020). "Therefore, adding PAX8 and SATB2 to the panel of immunostains for differentiating mucinous tumors will be of great benefit." (PMID 31771640, 2019). "Regarding mucinous tumors arising from the colon and appendix, the most sensitive marker is CDX2 (91.7%), while the most specific is SATB2 (98.0%)." (PMID 31771640, 2019).